ERICH2 (glutamate rich 2)
Tractability: No criterion of Open Targets' tractability assessment is met for any kind of drug.
Gene: Protein-coding gene on chromosome 2 (170,766,878 to 170,798,977, forward strand). Ensembl gene ENSG00000204334.
Subcellular location (Human Protein Atlas): Nucleoli fibrillar center; Vesicles
Gene Ontology:
Molecular function: protein binding
Genetic constraint (gnomAD): Loss-of-function variants: 3 observed, 4.79 expected, observed/expected ratio (o/e) 0.63, 90% interval 0.28 to 1.54. That is too few expected variants to judge how well the gene tolerates losing a copy. Missense variants: 62 observed, 64.33 expected, observed/expected ratio (o/e) 0.96, 90% interval 0.79 to 1.19. Synonymous variants: 18 observed, 21.6 expected, observed/expected ratio (o/e) 0.83, 90% interval 0.57 to 1.24.
Homologues: Orthologues: macaque ERICH2 (64% identical), rat Erich2 (47% identical), mouse Erich2 (47% identical), chimpanzee ERICH2 (33% identical), dog ERICH2 (33% identical), tropical clawed frog erich2 (18% identical), zebrafish erich2 (17% identical), Drosophila melanogaster CG14853 (11% identical).
Diseases named in the same sentence as ERICH2 in open-access papers:
ERICH2 is named in the same sentence as 1 disease in open-access papers, as found by Europe PMC text mining. Sharing a sentence is not in itself a finding about the gene and the disease. The quoted sentences say what the papers report.
cardiovascular diseases (1 paper, 2022). "In the dilated stage, TMEM205, ADIRF, C6H4orf48, NGRN, PROSER1, ERICH2, and CINP were not previously linked to cardiovascular diseases." (PMID 35625658, 2022).